ALDH2 (aldehyde dehydrogenase 2 family member)
Diseases named in the same sentence as ALDH2 in open-access papers (continued):
Sharing a sentence is not in itself a finding about the gene and the disease.
esophageal squamous cell carcinoma (21 papers, 2013 to 2024). Esophageal squamous cell carcinoma (ESCC) is a type of esophageal carcinoma (EC) that can affect any part of the esophagus, but is usually located in the upper or middle third. "The JEC study confirmed that slow‐metabolizing ADH1B was a predictor of the development of metachronous esophageal SCC after ER and inactive ALDH2 was also associated with the development of metachronous esophageal SCC." (PMID 37409321, 2023). "Meta-analyses of Asian case-control studies showed that female drinkers with the ALDH2*1/*2 genotype had an increased risk of esophageal SCC." (PMID 30629674, 2019). "The ALDH2*1/*2 genotype and alcohol flushing are associated with high acetaldehyde exposure after drinking, resulting in a high risk of esophageal SCC." (PMID 30629674, 2019). "Deficiency in functional ALDH2 was found to cause an alcohol-flushing response and increase the risk of alcohol-related esophageal SCC." (PMID 33748520, 2018). "Rs886205 (A>G) is an SNP in the promoter of ALDH2, which has been identified as a risk marker for esophageal squamous cell carcinoma in several Western populations." (PMID 28052001, 2017). "Higher risks of developing metachronous and multiple SCC in the UAT of Japanese subjects with esophageal SCC have been found to be associated with the presence of ALDH2*2, drinking, smoking, and lower fruit intake." (PMID 28384229, 2017). "Drinking and smoking have a synergistic effect in increasing the risk of esophageal SCC, but drinking combined with alcohol flushing or inactive ALDH2 has an even greater effect." (PMID 28384229, 2017). "However, a case-control study in Japanese women showed a markedly high risk of esophageal SCC in women with the ALDH2*1/*2 genotype who were heavy drinkers; this result was comparable to the results of a male study conducted simultaneously." (PMID 30629674, 2019). "ALDH2-related susceptibility to esophageal SCC has been demonstrated in Asian female drinkers." (PMID 28384229, 2017). "Finally, gene targets GSTO1 and ALDH2 are associated with breast, ovarian, and esophageal squamous cell cancer." (PMID 26472186, 2015). "Patients with inactive acetaldehyde dehydrogenase 2 (ALDH2) are at high risk for esophageal squamous cell carcinoma (ESCC) and hypopharyngeal squamous cell carcinoma (HPSCC)." (PMID 34010294, 2021). "The substantially increased risk of esophageal squamous cell carcinoma (ESCC) for ALDH2 deficient alcoholics has provided the most persuasive evidence for the carcinogenic potential of acetaldehyde in humans." (PMID 24058561, 2013). "Multivariate analysis showed that inactive ALDH2 (HR 2.25; 95% CI 1.18–4.59) was a significant predictor of the development of metachronous esophageal SCC or head and neck SCC." (PMID 37409321, 2023). "In this study, we selected superficial esophageal SCC cases treated with ESD, and performed a replication study to confirm the relationship between ESCC and the ADH1B & ALDH2 risk alleles by using an Invader assay." (PMID 27038040, 2016). "It has also been reported that inactive ALDH2*1/*2 and less-active ADH1B*1/*1, and smoking, are risk factors for esophageal SCC." (PMID 23667679, 2013). "On multivariate analysis, slow‐metabolizing ADH1B (hazard ratio [HR] 2.21; 95% confidence interval [CI] 1.1–4.45) and inactive ALDH2 (HR 3.28; 95% CI 1.28–11.15) were significant predictors of the development of metachronous esophageal SCC or head and neck SCC." (PMID 37409321, 2023).
esophageal squamous cell carcinoma (continued). "When current or former flushing individuals were considered to have inactive ALDH2, the sensitivity and specificity of the test were 84.8% and 82.3%, respectively, for the esophageal SCC patients and 90.1% and 88.0%, respectively, for the cancer‐free population." (PMID 37409321, 2023). "It has been calculated that if moderate or heavy drinking ALDH2 heterozygotes were instead only light drinkers, 53% of esophageal squamous cell carcinomas might be prevented in the Japanese male population." (PMID 25831092, 2015). "Comparison of detection rates of esophageal squamous cell carcinoma (ESCC) and gastric adenocarcinoma (GA) according to age groups and ALDH2 genotype between the 1993‐2007 screening period and the 2008‐2018 screening period in Japanese alcohol‐dependent men." (PMID 31957322, 2020). "A previous genome‐wide association study identified two novel esophageal squamous cell carcinoma (ESCC) susceptibility genes, ADH1B and ALDH2." (PMID 27038040, 2016). "Lower expression of ALDH2 was consistently observed in tumor tissue samples compared to normal tissues in five different cancer types including breast cancer, lung SCC, lung adenocarcinoma, head and neck SCC and esophageal SCC." (PMID 35330099, 2022). "Alcohol consumption combined with inactive aldehyde dehydrogenase-2 (ALDH2) and the presence of multiple esophageal Lugol-voiding lesions (LVLs; dysplasia) are strong predictors for multiple development of esophageal squamous cell carcinoma (ESCC) in East Asians." (PMID 28384229, 2017). "Not only alcohol and smoking but also genetic factors such as aldehyde dehydrogenase 2 (ALDH2) and alcohol dehydrogenase 1B (ADH1B) have been identified as risks for esophageal squamous cell carcinoma (ESCC)." (PMID 29285315, 2017).
Obesity (21 papers, 2016 to 2025). Accumulation of substantial excess body fat. "This underscores a broader cardioprotective potential against AF pathogenesis, indicating a promising avenue for further research into its role in AF development within the context of obesity and ALDH2 deficiency." (PMID 38396862, 2024). "Our findings unravel a complex interplay between the ALDH2*2 genetic variant, obesity, and associated complications such as AF." (PMID 38396862, 2024). "There is a consistent association with ALDH2 and obesity-related features including BMI, waist circumference, waist-to-hip ratio, and visceral fat accumulation." (PMID 38703299, 2024). "This study investigated the impact of ALDH2 deficiency on diet-induced obesity and AF vulnerability in mice, exploring potential compensatory upregulation of nuclear factor erythroid 2-related factor 2 (Nrf2) and heme-oxygenase 1 (HO-1)." (PMID 38396862, 2024). "This contrasts with a recent report indicating that ALDH2*2 homozygous KI male mice are predisposed to diet-induced obesity, presenting with glucose intolerance, insulin resistance, and fatty liver when exposed to a high-fat high-sucrose diet." (PMID 38396862, 2024). "Despite these insights, the intricate relationship between ALDH2 deficiency, obesity, and AF susceptibility remains elusive." (PMID 38396862, 2024). "Emphasizing this, the rise in ROS levels was more substantial in ALDH2*2 KI mice, accentuating their heightened susceptibility to oxidative stress under diet-induced obesity conditions." (PMID 38396862, 2024). "These unexpected findings emphasize the need for further investigation into the nuanced relationships between ALDH2 deficiency, obesity, and AF susceptibility." (PMID 38396862, 2024). "Further studies are warranted to unravel the intricate molecular mechanisms underlying the crosstalk between obesity, ALDH2, and cardiac health, shedding light on potential therapeutic targets for obesity-related cardiac complications." (PMID 38396862, 2024). "Addressing these limitations in future research will contribute to a more comprehensive understanding of the intricate relationship between ALDH2 deficiency, obesity, and AF susceptibility." (PMID 38396862, 2024). "This study seeks to investigate the impact of ALDH2 deficiency on diet-induced obesity and AF vulnerability." (PMID 38396862, 2024). "In previous studies conducted in China and East Asia, the ALDH2 mutant allele was significantly associated with obesity, increased BMI, and visceral fat deposition." (PMID 37240928, 2023). "Our study provides a feasible strategy by targeting ALDH2 for the treatment of obesity-associated metabolic disorders which are rising rapidly in human populations, particularly in the East and South Asia." (PMID 37749090, 2023). "We find that male Aldh2 knock-in mice mimicking human Glu504Lys mutation were prone to develop diet-induced obesity, glucose intolerance, insulin resistance, and fatty liver due to reduced adaptive thermogenesis and energy expenditure." (PMID 37749090, 2023). "A common East Asian-specific defect of an alcohol metabolizing enzyme (ALDH2) causes glucose abnormality, obesity, and fatty liver." (PMID 37749090, 2023). "We showed that reduced activity of the mitochondrial enzyme, ALDH2, exacerbates obesity-associated pathologies." (PMID 37749090, 2023). "Meta-analysis of GWAS in East Asian populations showed associations between the SNP ALDH2 rs671 and obesity and various cardiovascular risk factors and coronary artery disease (CAD)." (PMID 29016630, 2017). "It has been reported that ALDH2 expression negatively correlates with obesity in mice while 4-HNE accumulation is positively associated with obesity and is increased in terminal adipocyte differentiation." (PMID 27575855, 2016).
Obesity (continued). "It is worth noting that the SNP rs12229654 at MYL2 and its related SNP rs671 at ALDH2 were associated with every obesity trait analyzed (WCadjBMI, WHRadjBMI, WCnoBMI, and WHRnoBMI), with larger effects observed in men." (PMID 26785701, 2016). "Previous GWASs have suggested that ALDH2*2’s association with obesity and cardiovascular risk factors may be influenced by alcohol consumption habits." (PMID 38396862, 2024). "There might be additional compensatory regulatory pathways associated with ALDH2 deficiency to counteract susceptibility to obesity-related AF." (PMID 38396862, 2024). "Finally, our study did not explore the potential role of electrical remodeling in AF susceptibility within the context of ALDH2 deficiency and diet-induced obesity." (PMID 38396862, 2024). "Future investigations combining an HFD and chronic alcohol consumption in our mouse model, along with a broader spectrum of pacing approaches, could enhance understanding of AF susceptibility in obesity with ALDH2 deficiency." (PMID 38396862, 2024). "In view of the marked reduction in Aldh2 expression in diet-induced obese mice, we next explored whether Aldh2 activation can rescue these obesity-associated phenotypes." (PMID 37749090, 2023). "ALDH2 detoxifies cells of lipid end products-reactive aldehydes such as 4-HNE that accumulate with a high-fat diet, and the Aldh2-/-Sptbn1+/- mice provided new insight into the role of obesity in promoting HCC." (PMID 40269686, 2025). "More recently, we have uncovered obesity-driven HCC in our mouse models with disruption of TGF-β signaling and loss of aldehyde dehydrogenase 2 (Aldh2)." (PMID 40269686, 2025). "More recently, we have uncovered obesity-driven cancers in our mouse models with disruption of TGF-β signaling and loss of aldehyde dehydrogenase 2 (Aldh2)." (PMID 40311681, 2025). "Our study aligns with these findings, revealing that diet-induced obesity leads to suppressed ALDH2 production, resulting in increased 4-HNE-related oxidative stress and heightened vulnerability to AF." (PMID 38396862, 2024). "Further comprehensive investigations are warranted to unravel the intricate interplay between ALDH2*2, diet-induced obesity, and the broader spectrum of metabolic parameters." (PMID 38396862, 2024). "Recently, a novel and highly selective ALDH2 activator, AD-9308, has emerged, demonstrating promising outcomes in addressing diet-induced obesity and fatty liver and enhancing glucose homeostasis in both ALDH2 wild-type and mutation mice." (PMID 39226171, 2024). "To scrutinize the influence of ALDH2*2 on obesity-related oxidative stress, we examined the interplay between ALDH2*2, fat deposition, and oxidative stress within mouse atria subjected to chronic HFD consumption." (PMID 38396862, 2024). "This expands the narrative surrounding ALDH2*2, emphasizing its role not only in alcohol-related health risks but also in the broader context of cardiovascular remodeling influenced by obesity." (PMID 38396862, 2024). "Further studies, incorporating multi-omics and gut microbiota analyses, are needed to untangle ALDH2*2′s decoupling of excess AF inducibility from obesity." (PMID 38396862, 2024). "Such endeavors will enhance our understanding of the clinical implications of ALDH2*2 in obesity-related metabolic disturbances, paving the way for more-targeted therapeutic strategies." (PMID 38396862, 2024). "Aldehyde dehydrogenase 2 (ALDH2), an enzyme involved in detoxifying aldehydes, is a potential player in obesity-related AF pathogenesis." (PMID 38396862, 2024). "By shedding light on these mechanisms, our research aims to unravel the involvement of ALDH2 in the complex interplay between obesity, oxidative stress, and AF, providing valuable insights into potential therapeutic targets." (PMID 38396862, 2024). "This intricate interplay between ALDH2 and 4-HNE highlights the impact of genetic mutations on oxidative stress responses in the context of diet-induced obesity." (PMID 38396862, 2024).
Obesity (continued). "AD-9308 treatment ameliorates diet-induced obesity and fatty liver, and improves glucose homeostasis in both male Aldh2 wild-type and knock-in mice." (PMID 37749090, 2023). "Building on these mechanistic insights, the current in vivo study targeting CVEC-specific ALDH2 overexpression in an obesity–T2DM-driven HFpEF model demonstrates for the first time that directly modulating endothelial oxidative resilience translates into functional cardiac benefits." (PMID 40723901, 2025). "Our goal was to determine whether enhancing aldehyde detoxification in CVECs through targeted ALDH2 overexpression improves cardiac function in a preclinical model of HFpEF driven by obesity-induced T2DM." (PMID 40723901, 2025). "In summary, ALDH2 deficiency did not heighten AF susceptibility in obesity, highlighting Nrf2/HO-1 pathway activation as an adaptive mechanism." (PMID 38396862, 2024). "Administration of Alda-1/chaetocin, aimed at enhancing ALDH2 activity, exhibited therapeutic potential by mitigating the impact of palmitic acid on autophagy and contractile function, suggesting a broader role for ALDH2 in obesity-related cardiomyopathy." (PMID 38396862, 2024). "In obesity, characterized by elevated oxidative stress and ROS accumulation, the demand on ALDH2 for the detoxification of acetaldehyde, a toxic byproduct of metabolism, may increase." (PMID 38396862, 2024). "Contrary to expectations, ALDH2 deficiency did not significantly heighten AF susceptibility in obesity; instead, the activation of the Nrf2/HO-1 pathway suggests an adaptive mechanism." (PMID 38396862, 2024). "Additionally, we did not elucidate the detailed signaling mechanisms explaining the reduced AF inducibility in ALDH2*2 mice with obesity." (PMID 38396862, 2024). "Previous research has shown that high-fat intake aggravatescardiac remodeling, including hypertrophy and interstitial fibrosis.Mitochondrial aldehyde dehydrogenase (ALDH2) serves an indispensable role inprotecting against cardiac anomalies from high-fat-induced obesity by enhancingautophagy." (PMID 39077569, 2023). "ALDH2 may counteract reactive oxygen species (ROS)-induced lipid aldehyde formation, which has been described in obesity and insulin resistance." (PMID 35058800, 2021). "High-fat diet feeding to C57BL/6 and ALDH2*2 mice resulted in increased body weight (obesity)." (PMID 29677191, 2018). "In the present study, to our best knowledge, we show for the first time that the level of ALDH-2 inhibition is directly correlated with the superoxide formation rate in the human myocardium and that its expression is negatively influenced by obesity." (PMID 30647815, 2018). "ALDH2 expression in white adipose tissue is negatively correlated with obesity." (PMID 27575855, 2016). "We also investigated whether ALDH2 levels were altered in murine models of obesity." (PMID 27575855, 2016). "Thus, modulation of ALDH2 expression and/or its activity in white adipose tissue might provide a novel avenue in treating obesity and related metabolic disorders." (PMID 27575855, 2016). "Thus, activation of PKCε-ALDH2 regulatory axis may be a therapeutic target for treating obesity and type 2 diabetes." (PMID 27575855, 2016). "ALDH2 detoxifies cells of lipid end products—reactive aldehydes such as 4-HNE that accumulate with a high-fat diet (HFD), and the Aldh2−/−Sptbn1+/− mice provided new insight into the role of obesity in promoting cancer." (PMID 40311681, 2025). "Although WIN 18,446 is not currently a viable drug for obesity or male contraception due to its inhibitory effects on ALDH2 which is critical in alcohol metabolism, it is a potent tool to decipher the role of RA in health and disease, including IBD." (PMID 32987910, 2020). "First, obesity and related metabolic phenotypes in the Aldh2 KI mice were observed only when fed on HFHSD and not when placed on chow diet, the metabolic phenotypes were not different between the Aldh2 KI and WT mice." (PMID 37749090, 2023).